MSC-AS1 (MSC antisense RNA 1)
Synonyms: MAT1
Gene: Long non-coding RNA gene on chromosome 8 (71,828,167 to 72,118,393, forward strand). Ensembl gene ENSG00000235531.
Diseases named in the same sentence as MSC-AS1 in open-access papers:
MSC-AS1 is named in the same sentence as 1 disease in open-access papers, as found by Europe PMC text mining. Sharing a sentence is not in itself a finding about the gene and the disease. The quoted sentences say what the papers report.
cancer (1 paper, 2022). A tumor composed of atypical neoplastic, often pleomorphic cells that invade other tissues. "Musculin antisense RNA 1 (MSC-AS1) is a lncRNA, which interacts largely with miRNAs and acts as an oncogene in several cancers." (PMID 35480307, 2022).